EGFR (epidermal growth factor receptor)
Diseases named in the same sentence as EGFR in open-access papers (continued):
Sharing a sentence is not in itself a finding about the gene and the disease.
diabetes (continued). "EGFR regulates endothelial proliferation, permeability, and tube formation, while its abnormal activation contributes to oxidative stress–related endothelial dysfunction in diabetes." (PMID 41438739, 2025). "For instance, in diabetes mellitus, where patients are at heightened risk for atherosclerosis, BMECs chronically downregulate HSC-protective factors CXCL12 and Ang-1 due to disrupted epidermal growth factor receptor (EGFR) signaling." (PMID 40376111, 2025). "EGFR is thus considered a potential target in diabetes-related complications." (PMID 41459066, 2025). "Hypertension, diabetes, history of cardiovascular and cerebrovascular diseases, and history of smoking were risk factors for prognosis after EGFR-TKI therapy, though this trend was not statistically significant." (PMID 39071492, 2024). "Importantly, inhibition of EGFR seems sufficient to correct many of the hyperglycemia/diabetes-induced hemodynamic, morphological, and renal cell signaling changes associated with DN." (PMID 39234105, 2024). "Research has demonstrated that the kidneys exhibit a high level of EGFR, and that diabetes may be prevented by blocking the EGFR signaling pathway." (PMID 39194535, 2024). "PI3K acts as an effector of EGFR in diabetes-induced vascular dysfunction." (PMID 37374078, 2023). "Similarly, subgroup analyses were performed focusing on patients receiving EGFR-TKI treatment (according to comorbidity of diabetes mellitus) and diabetic patients (according to treatment type)." (PMID 36969876, 2023). "However, under pathological conditions, EGFR inhibition can be cardioprotective, as EGFR has been shown to be upregulated in diabetes." (PMID 36795511, 2023). "In a study on corneal epithelialization in the context of diabetes, high-glucose attenuated wounds had enhanced LL-37 expression, which in response, prolonged the effects of epidermal growth factor receptor (EGFR) signaling and its ability to hasten scratch wound closure." (PMID 35722307, 2022). "NOTCH3 EGFr group is followed in importance by sex, hypertension, diabetes, and smoking." (PMID 35862191, 2022). "We also discussed metabolic vulnerabilities that could be addressed by already FDA-approved drugs used for other diseases such as hyperlipidemia and diabetes, thus accelerating their introduction into clinical use for EGFR TKI-treated patients." (PMID 35203491, 2022). "A summary of selected studies implicating EGFR signaling in diabetes-induced vascular dysfunction." (PMID 34408653, 2021). "Probably the early clues to the involvement of EGFR/ErbB receptors in diabetes-induced complications were the observation that excretion of EGF ligand was abnormal in many patients with diabetes and that EGF gene expression was elevated in the mesenteric artery of rats bearing type 1 diabetes." (PMID 34408653, 2021). "Thus, FOXO-mediated pro-apoptotic signaling is likely an important downstream contributor to EGFR/ErbB receptor-mediated vascular dysfunction in diabetes." (PMID 34408653, 2021). "Additionally, SAHA can reduce diabetes-mediated kidney enlargement by downregulating epidermal growth factor receptor (EGFR) expression." (PMID 34071497, 2021). "Diabetes-induced vascular dysfunction arising from enhanced EGFR/ErbB2 signaling also led to downstream activation of FOXO3 (as evidenced by reduced phosphorylation at Ser253) through an AKT-independent manner that ultimately leads to apoptosis and vascular dysfunction." (PMID 34408653, 2021). "The fact that significant attenuation of these pathological changes occurred after treatment with gene silencing shRNAs or EGFR inhibitors provided strong evidence that aberrent EGFR signaling plays a crucial role in the pathogenesis of cardiac dysfunction and remodeling in diabetes." (PMID 34408653, 2021). "Nonetheless, collectively these studies suggest that targeting of EGFR and ER stress may represent novel therapeutic strategies in the potential treatment of diabetes-induced cardiac pathologies." (PMID 34408653, 2021).
diabetes (continued). "Despite disturbed vascular response, EGFR also mediates vascular remolding in diabetes." (PMID 33574751, 2020). "Besides the targeting of VEGFA/VEGFR1, vandetanib’s target EGFR can also potentially help diabetes pathology." (PMID 32764756, 2020). "Lapatinib is a dual inhibitor of EGFR and ErbB2 receptor tyrosine kinases, by which high glucose-induced apoptosis and vascular dysfunction were refined via resistance to signaling changes influenced by diabetes in the experimental T1D models." (PMID 33841528, 2020). "However, an important link of EGFR and diabetes has been identified before: elevated levels of ErbB2 are associated with hyperglycemia and impaired insulin sensitivity." (PMID 31815004, 2019). "Similarly, genes ESR1, SERPINE1 and VEGFA are shared across diabetes (EGFR, GSTP1, SERPINE1, ESR1, VEGFA and EGF) and obesity (CCND1, SERPINE1, ESR1 and VEGFA), which is in line with previous reports that obesity is a risk factor of diabetes." (PMID 31835887, 2019). "EGFR activation has also been involved in the vascular complications of diabetes." (PMID 30670929, 2018). "PF treatment prevented diabetes-induced EGFR phosphorylation." (PMID 29221204, 2017). "Indeed the EGFR signaling pathway appears important in both normal and pathological states such as cancer and diabetes-induced renal and cardiovascular dysfunction." (PMID 26167903, 2015). "We previously showed that the dysregulation of ErbB receptor tyrosine kinases appears to be an important early initiation step in the development of diabetes-induced vascular dysfunction that involves increased gene-expression and enhanced phosphorylation of EGFR and ErbB2 receptor tyrosine kinases." (PMID 26536590, 2015). "For example, PF might be useful in reversing diabetes-induced renal and vascular dysfunction where overactivity of EGFR is noted." (PMID 26167903, 2015). "Alternatively, SF might be used in place of conventional ligand-activation based therapeutic strategies to stimulate EGFR signaling in diabetes-induced cardiac dysfunction which results from depressed EGFR-ERK1/2 phosphorylation." (PMID 26167903, 2015). "Interestingly, EGFR was reported recently to be responsible for improvement of cardiac recovery in diabetic hearts, as diabetes led to attenuated dimerization and phosphorylation of the EGFR." (PMID 24086307, 2013). "However, the extent of cardiac dysfunction-induced by the inhibitors appeared to be greater in normal compared to diabetic hearts implying that the EGFR/erbB2 pro-survival pathway was significantly impaired in diabetes." (PMID 22720029, 2012). "In the other case, EGFR promotes the upregulation of β-cell proliferation as a response after inflammation due to injuries, including surgical pancreas remotion or high-fat diet that promotes insulin resistance, suggesting its function as a therapeutic diabetes target." (PMID 39966897, 2025). "Therefore, increasing β-cell proliferation is a therapeutic strategy for diabetes treatment, and the upregulation of EGFR could be crucial for the improving β-cell function." (PMID 39966897, 2025). "Additionally, the EGFR signaling pathway plays a crucial role in regulating cell growth, proliferation, migration, and differentiation, both in normal and disease states such as cancer and diabetes-related cardiovascular dysfunction." (PMID 38654922, 2024). "However, the expression level of HSP60 was not significantly related to the following clinicopathological parameters: age, sex, diabetes mellitus, family history, smoking, anemia, WBCs count, serum CEA level, tumor location, TNM classification, or EGFR mutation." (PMID 37627080, 2023). "Although genetic manipulation of pancreatic EGFR in mice leads to the acceleration or prevention of diabetes, the natural history of EGFR kinase activity during different phases of the progression to diabetes remains unknown." (PMID 37233668, 2023).
diabetes (continued). "However, subgroup analysis based on treatment type and comorbidity of diabetes mellitus showed that the effect of improved OS was observed only for patients receiving EGFR-TKIs (HR = 0.73, 95% CI: 0.57–0.94, p = 0.013) and those with diabetes mellitus (HR = 0.74, 95% CI: 0.62–0.88, p = 0.001)." (PMID 36969876, 2023). "There was no statistical significance in the association between EGFR mutation and the following variables: age, gender, smoking, region, subtype, metastasis, diabetes mellitus, hypertension, dyslipidemia, ischemic heart disease, and benign prostatic hyperplasia." (PMID 34963835, 2021). "Additionally, concomitant disease states such as diabetes might affect the advantage of EGFR inhibition on cardioprotection." (PMID 34404849, 2021). "Since it is now known that GPCRs can initiate transactivation of the EGFR, which is expressed in both endothelial cells and VSMCs, there is strong indications that EGFR signalling may also be a key player in mediating vascular pathology in diabetes." (PMID 34408653, 2021). "Moreover, it has recently been shown that EGFR transactivation is also involved in ROS generation and cell apoptosis induced by high concentrations of glucose in rat cardiomyocytes, thus pointing to its participation in diabetes-induced cardiac injury." (PMID 32046347, 2020). "Therefore, we believe vandetanib could be considered as a potential diabetes treatment, due to its ability to target EGFR leading to a possible decrease in inflammatory cytokine production." (PMID 32764756, 2020). "Therefore, such multitarget tyrosine inhibitors, initially developed for their potent anticancer effects, have been previously proposed for the treatment of diabetes, such as the potent EGFR inhibitors erlotinib and PD153035 with robust antihyperglycemic effects." (PMID 31815004, 2019). "Likewise, we previously reported that pan-HDAC inhibition attenuates renal growth in early experimental diabetes; a finding that we attributed to downregulation of the epidermal growth factor receptor (EGFR), which may itself be regulated by HDAC6." (PMID 29449811, 2018). "Furthermore, treatment of an EGFR inhibitor (PD153035) improves glucose intolerance and insulin sensitivity and reduces inflammation in diet-induced obese (DIO) mice, indicating the some roles of the EGFR signaling pathway in the pathophysiologies of diabetes mellitus." (PMID 28053990, 2016). "Indeed, recent report suggests that EGFR-induced ER-stress might lead to vasculature dysfunction and cardiac fibrosis in experimental diabetes." (PMID 23826343, 2013). "Thus, RU-mediated blockade of aldosterone-induced EGFR transactivation may be beneficial in improving diabetes-induced vascular dysfunction in the heart but this requires further study." (PMID 24066305, 2013). "It was found that nine active ingredients in sweet potato leaves act on 90 targets related to diabetes, with the main targets for their blood glucose-lowering effects being AKT1, GAPDH, STAT3, TNF, and EGFR." (PMID 41515064, 2026). "SRC/EGFR/FYN, on the other hand, provides some therapeutic leverage, but it more specifically addresses diabetes-related complications." (PMID 41011980, 2025). "Thus, therapeutic targeting of one or more EGFR/ErbB receptors might be useful in correcting diabetes-induced renal vascular dysfunction as well as for reversing the underlying morphological changes and alterations in key renal cell signaling cascades typically associated with DN." (PMID 39234105, 2024). "Among the top 20 core targets, 5 targets (STAT3, PIK3CA, AKT1, EGFR and VEGFA) were closely related to diabetes." (PMID 38921004, 2024). "The results offer us a comprehensive understanding of the therapeutic effects of previously identified target proteins, including AKT1, IL6, PPARG, JUN, CASP3, EGFR, and PTGS2, in the context of diabetes intervention." (PMID 39707185, 2024).
diabetes (continued). "HBEGF signals by binding to the epidermal growth factor receptor (EGFR), which plays important roles in tumorigenesis, metabolic diseases, diabetes, pain-related diseases, and Alzheimer’s disease." (PMID 36894989, 2023). "The analysis of individual studies on miR-146 in the context of diabetes yielded a heatmap that showcased the prevalence of several genes, namely IRAK1, TRAF6, IL-6, TNF-α, NUMB, EGFR, and TGFβ-1, among others." (PMID 37560309, 2023). "After adjusting for sex, age, diabetes duration, Alb, BUN, EGFR and HbA1c, the relationship between TIR and BaPWV remained(P<0.05) (Model 3)." (PMID 36325447, 2022). "Treatment of valproic acid for 8 weeks significantly attenuated diabetes-induced expression of p21 and the SASP markers Il-6, TNF-α, EGFR and Fn." (PMID 36434087, 2022). "Our results show that NOTCH3cys EGFr group is the most important modifier of CADASIL known to date, followed by male sex, hypertension, diabetes, and smoking." (PMID 35862191, 2022). "For example, diabetes enhances phosphorylation of EGFR1 and ErbB2, formation of EGFR/ErbB2 heterodimers and subsequent elevation in ERK1/2 and ROCK signaling leading to dysfunction in the mesenteric vasculature of T1DM rats." (PMID 34408653, 2021). "Taken together, these studies suggest an important role of hyperglycemia-induced Src-dependent transactivation of EGFR/ErbB receptors and a downstream ROCK-dependent pro-contractile action in mediating diabetes-induced vascular dysfunction." (PMID 34408653, 2021). "Further, since vascular proliferation and remodeling (e.g., via hypertrophy, hyperplasia and fibrosis) leads to altered vascular contractility in diabetes, of note were the studies showing a pro-contractile role for EGF/EGFR signaling." (PMID 34408653, 2021). "In particular, PAMAM dendrimers were able to inhibit the epidermal growth factor receptor (EGFR)-ERK1/2-ROCK pathway, a key player in the development of vascular abnormalities in diabetes." (PMID 34069422, 2021). "Collectively these studies provide a direct link between EGFR and NADPH oxidase in mediating oxidative stress that leads to diabetes-induced vascular dysfunction." (PMID 34408653, 2021). "The cumulative incidence of successful weaning rate was higher among the patients harboring EGFR deletion 19 mutation than those with L858R or other uncommon mutations, with a log-rank p value of 0.016; it was also higher in the patient without diabetes mellitus (DM) (log-rank p value < 0.001)." (PMID 34680533, 2021). "Some studies using experimental mouse models reported that epidermal growth factor receptor (EGFR) mRNA expression is down-regulated in pancreatic islet cells and related to onset of diabetes." (PMID 32956382, 2020). "AG1478 inhibited EGFR and AKT activation, ameliorating ROS accumulation and ER stress and preventing diabetes-induced renal injury." (PMID 28427241, 2017). "Beyond Ripk2, there is evidence for the involvement of other proteins targeted by TKI in pre-diabetes and diabetes, such as c-Abl, PDGFR, EGFR and VEGFR2." (PMID 28484277, 2017). "Our previous studies also showed that metformin could enhance EGFR-TKI sensitivity in EGFR-TKI resistant NSCLC cells, metformin use was associated with improved survival and delayed onset of acquired resistance to EGFR-TKI in patients with NSCLC and diabetes mellitus type 2." (PMID 29212192, 2017). "Transactivation of the epidermal growth factor receptor (EGFR or ErbB) family members, namely EGFR and ErbB2, appears important in the development of diabetes-induced vascular dysfunction." (PMID 26536590, 2015). "Hence EGFR blockade may hold promise, not only in limiting tubulointerstitial pathology in diabetic nephropathy, but also in limiting the sodium and water retention observed in patients with diabetes and exacerbated by PPARγ agonists." (PMID 23533381, 2013).
diabetes (continued). "From this diabetic nephropathy sub-network module we have proposed the two putative interactions of PTPN1 with EGFR and CAV1 which have been highlighted for the first time in diabetes condition." (PMID 19997558, 2009). "Sub-network from obesity and diabetes datasets indicate the significant roles of SUMO4, GAPDH and EGFR interactions in insulin signalling diabetes progression." (PMID 19997558, 2009). "KCLE also improves diabetes by regulating AKT1, TNF, EGFR, and GSK3β." (PMID 40076380, 2025). "Similarly, epidermal growth factor (EGF), which activates the epidermal growth factor receptor (EGFR), is involved in diabetes onset, vascular dysfunction, and the pathogenesis of type 2 DM." (PMID 38654922, 2024). "We previously reported that in EGFR mutant NSCLC without diabetes, metformin in combination with gefitinib resulted in non-significantly worse outcomes but increased the risks of diarrhea." (PMID 35281267, 2022). "Mechanistic studies from our group identified that EGFR signaling via multiple pathways including those already known to be involved in pain signaling, such as MAP kinases and PI3K/AKT, were critical mediators of diabetes-induced microvascular dysfunction." (PMID 32547536, 2020). "While neratinib is not at all selective for MST1, we believe that the underlying mechanisms of diabetes protection still derive from a direct protective effect on the β-cell mediated by MST1 and not from an effect on insulin sensitivity mediated by EGFR." (PMID 31676778, 2019). "Therefore, it is possible that diabetes-induced increased 11β-HSD1 and glucocorticoids mediate cardiac fibrosis through engaging the EGFR pathway." (PMID 29221204, 2017). "Therefore, it is possible that diabetes and high levels of glucose increase local glucocorticoid levels which induce ADAM12 and increase EGF-EGFR interaction leading to EGFR phosphorylation and activity." (PMID 29221204, 2017). "Western blotting analyses showed that hearts isolated from STZ-induced diabetes, but not exposed to I/R, exhibited significantly reduced phosphorylation of EGFR and erbB2 at multiple tyrosine (Y) residues." (PMID 22720029, 2012). "Inhibited EGFR/PI3K/AKT signaling pathway, reduced the released of inflammatory factors IL-1β, IL-6, TNF-αImproved lipid and glucose metabolism, promoted adipogenesis, improved insulin sensitivity by regulating PI3K-Akt signaling pathway, and fight against diabetes and its complications." (PMID 41356003, 2025). "The results of our research suggest that EGFR, CCL2, PTGS2 and SERPINE1 proteins that play a significant role in the diabetic cardiomyopathy network may function as a druggable node to impact the repercussions of diabetes in cardiomyocytes." (PMID 40282226, 2025). "The ten important active constituents were chosen for molecular docking verification with the key targets TNF, AKT1, EGFR, and GSK3β (the core intersection target of the PPI network and Component-pathway-target network), which are considered potential targets in the treatment of diabetes." (PMID 40076380, 2025). "However, subgroup analysis based on treatment type and comorbidity of diabetes mellitus demonstrated that improvements in OS and PFS were observed only in diabetic and EGFR-TKI-treated patients (OS: HR = 0.64, 95% CI: 0.45–0.90, p = 0.011; PFS: HR = 0.59, 95% CI: 0.34–1.03, p = 0.061)." (PMID 36969876, 2023). "This clinical case reports the combination of HER2/EGFR/MST1-inhibition by neratinib for the pharmacological intervention to effectively restore normoglycemia in a patient with poorly controlled T2D and suggests neratinib as potent therapeutic regimen for the cancer-diabetes comorbidity." (PMID 35370966, 2022). "A greater understanding of the multi-faceted roles of EGFR/ErbB/HER family of tyrosine kinases and their interplay with other key modulators of cardiovascular function could facilitate the development of novel therapeutic strategies for treating diabetes-induced cardiovascular complications." (PMID 34408653, 2021).